ATF4 (activating transcription factor 4)
Diseases named in the same sentence as ATF4 in open-access papers (continued):
Sharing a sentence is not in itself a finding about the gene and the disease.
liver cancer (21 papers, 2013 to 2025). An epithelial or non-epithelial malignant neoplasm that arises from the liver. "RBBP8 or ATF4 protein expression were potentially diagnostic markers and therapeutic targets of liver cancer." (PMID 37591836, 2023). "TCGA database showed that both RBBP8 and ATF4 mRNA levels were highly expressed in multiple cancer types, including liver cancer, and demonstrated its association with a shorter life span in HCC patients, and RBBP8 expression was highly expressed in either Ki67-positive regions or positive cells." (PMID 37591836, 2023). "Besides, RBBP8 was positively associated with ATF4 expression in liver cancer." (PMID 37591836, 2023). "In contrast, TRIB3 can repress certain TFs, as seen in liver cancer cells treated with bortezomib, where it binds to ATF4 on chromatin." (PMID 41287970, 2025). "Together, these results indicate that both ALKBH5 and FTO regulate the expression of ATF4 in liver cancer cells treated with SOR." (PMID 39199320, 2024). "For example, piperlongumine induces the apoptosis of liver cancer cells by upregulating the ferroptosis-inducing ATF4 gene." (PMID 38892270, 2024). "Dihydroartemisinin promotes the antiproliferation and ferroptosis of liver cancer cells by upregulating the ferroptosis-inducing ATF4 gene and downregulating ferroptosis-inhibiting genes (GPX4, SLC7A11, and SLC3A2)." (PMID 38892270, 2024). "Then ATF4 expression in liver cancer was analyzed by immunostaining, showing that ATF4 protein expression was significantly higher in Ki67-positive region and Ki67-positive cells." (PMID 37591836, 2023). "RBBP8 expression was also analyzed in multiple liver cancer cell lines at basal or cell cycle synchronized cells, showing that RBBP8 was positively associated with ATF4 expression at the protein level." (PMID 37591836, 2023). "We found that the pseudokinase TRIB3, an endogenous regulator of ATF4 and a gene highly expressed in liver cancer, resides predominantly at the same chromatin sites as ATF4 and constrains ATF4 activity." (PMID 34066165, 2021). "We found that the PERK-eIF2α-ATF4-CHOP pathway was inhibited in liver cancer cells after treatment with 125I and LBP." (PMID 31582720, 2019). "The pathway from AhR to VEGF through ATF4 is a novel pathway in glucose-deprived liver cancer cells, which is related to the microenvironment within cancer tissue that affects liver cancer malignancy." (PMID 24330582, 2013). "The AhR-VEGF pathway through ATF4 is a novel pathway in glucose-deprived liver cancer cells that is related to the microenvironment within a cancer tissue affecting liver cancer malignancy." (PMID 24330582, 2013). "With the downregulation of ATF4, miR-214-3p promotes erastin-triggered ferroptosis and the cell death of liver cancer cells, and miR-3200-5p improves ferroptosis and inhibits the proliferation and metastasis of liver cancer cells." (PMID 38892270, 2024). "(−)-Agelasidine A (derived from Agelas nakamurai) induced cytotoxicity in HepG2 and Hep3B liver cancer cell lines (with IC50 values of 129 μM and 69.9 μM, respectively), associated with apoptotic features and ER stress (elevated levels of GRP78, CHOP, ATF4, and p-PERK)." (PMID 38132936, 2023). "miR-3200-5p regulates liver cancer progression by targeting ATF4 to induce ferroptosis." (PMID 37008632, 2023). "Interestingly, ATF4 mRNA was highly expressed in various tumors, including liver cancer, and its expression level was negatively correlated with patient survival." (PMID 37591836, 2023). "Furthermore, Hu and associates showed that Metformin could enhance the sensitivity of liver cancer cells to Sorafenib via the ATF4/STAT3 signaling pathway." (PMID 40583627, 2025). "At the same time, ATF4 and STAT3 inhibitors may have further applications in sorafenib-resistant liver cancer patients, and understanding the role of ATF4/STAT3 molecular pathways in HCC progression will contribute to the development of potential drugs for targeted treatment of liver cancer." (PMID 37326750, 2023).
liver cancer (continued). "Another study found that liver cancer cell ferroptosis can be induced by suppressing HULC, mediated by the miR-3200-5p/ATF4 axis." (PMID 39267831, 2024). "Links between metabolic state and ATF4 induction have been previously observed in other in vitro studies, including the observation that ATF4 is induced upon ETC inhibition in neuronal, liver cancer cells and iPSC induced proximal tubular-like cells." (PMID 37353587, 2023). "In liver cancer, ER stress enhanced the transcriptional activation of FGF19 mediated by ATF4, and antiapoptotic ability was observed to increase during ER stress." (PMID 33981224, 2021). "(−)-Agelasine D (derived from the Agelas sponge) induced a potent cytotoxic response across a series of liver cancer cell lines (with a GI50 of 9.9 μM), which coincided with the induction of ER stress (elevated levels of p-ERK and ATF4 proteins) in Hep3B cells." (PMID 38132936, 2023). "Thus, liver cancer provides a model to study the physiological roles of RBBP8 and ATF4 in human disease." (PMID 37591836, 2023). "Interestingly, overexpression of RBBP8 in vitro promoted ATF4 activation under ER stress, and RBBP8 expression showed a positive correlation with ATF4 expression in liver cancer tissues by co-immunostaining." (PMID 37591836, 2023). "To study the pathological role of RBBP8 in regulating ATF4 activity, we illustrated that both RBBP8 and ATF4 were highly expressed in liver cancer tissues compared with healthy controls and highly expressed in Ki67-positive proliferating cells within the tumors." (PMID 37591836, 2023). "More importantly, the genetic nanomedicine not only inhibited liver cancer cell proliferation but also promoted liver cell apoptosis by slowing ROC1 activity, suppressing the Neddylation pathway, enabling the accumulation of apototic factor ATF4 and DNA damage factor P-H2AX." (PMID 34654435, 2021). "Our study showed that the expression levels of ER stress markers, including GRP78, PERK, IRE1α, ATF6, ATF4, XBP1S and CHOP, significantly increased with increasing concentration and duration of sorafenib treatment, suggesting that sorafenib can induce ER stress in liver cancer cells." (PMID 31523192, 2019). "Based on the results of isobaric tag for relative and absolute quantification labeling (iTRAQ) and the function of PERK-eIF2α-ATF4-CHOP pathway, we hypothesized that 125I seeds might induce the upregulation of PERK-eIF2a-ATF4-CHOP pathway, resulting in apoptosis in liver cancer cells." (PMID 31582720, 2019).
steatosis (19 papers, 2017 to 2025). Increased lipid within the cytoplasm of cells. "Hepatocyte ATF4 ablation inhibited hepatic steatosis, but increased susceptibility to ferroptosis, resulting in accelerated HCC development." (PMID 36996941, 2023). "Consistent with a pathogenic role in NAFLD, ATF4-deficient mice are protected against high-carbohydrate diet-induced steatosis, and ATF4-overexpressing zebrafish developed steatosis." (PMID 37373143, 2023). "Notably, this pathway is known to regulate lipogenesis and steatosis with ATF4-deficient mice exhibiting decreased synthesis of fatty acids and lower triglyceride serum levels." (PMID 33467546, 2021). "Interestingly, ATF4 deficiency or ATF4 knockdown can also protect the liver from diet-induced and ethanol-induced steatosis in mice." (PMID 30388740, 2018). "Another potential beneficial effect of 2′-FL that may have contributed to the observed decrease in steatosis is the counter regulation of several important factors associated with ER stress such as ATF4, ATF6, ERN1, NUPR1 indicating an overall attenuation of the ER stress response." (PMID 35782914, 2022). "A subsequent study using the same mouse model showed that BAP31 deficiency increased p-eIF2α, activating transcription factor 4 (ATF4) and C/EBP homologous protein (CHOP) expression and exacerbated tunicamycin-induced ER stress-associated steatosis." (PMID 41465598, 2025). "The PERK–eukaryotic initiation factor 2 alpha (eIF2α)–ATF4 pathway was shown to enhance lipogenesis and hepatic steatosis." (PMID 34237916, 2022). "Strong evidence has demonstrated that zinc can act directly on the liver and keep the liver from steatosis and apoptosis by inhibition of the eIF2α/ATF4/CHOP-mediated ER stress pathway." (PMID 34307690, 2021). "The SAPK/JNK phosphorylation levels were also increased in the liver of Ptcd1+/- mice fed a HFD compared to controls, despite the decrease in liver steatosis but consistent with the increased transcriptional activation of Atf4, Atf5 and Chop." (PMID 33024056, 2020). "Consistent with the antihepatic steatosis effects, exercise also significantly reduced the expressions of phosphorylated eIF2α and ATF4 proteins in the WT mice." (PMID 33299856, 2020). "In contrast, a direct role for the PERK-peIf2α -ATF4 pathway has been established in steatosis in mouse models and corroborated in human." (PMID 28797121, 2017). "The PERK-eIF2α-ATF4 arm was reported to regulate lipogenesis and steatosis." (PMID 38216941, 2024). "Similarly, transgenic overexpression of ATF4 results in increased lipid accumulation, leading to hepatic steatosis in zebrafish." (PMID 30388740, 2018). "When we silenced GRP94, the regulatory effects of AB23A on TG levels, cellular steatosis, ERS‐related proteins (p‐PERK/PERK, p‐eIF2α/eIF2α, ATF4), and ERAD‐related proteins (FBXO2, DERL, HSP90α) disappeared." (PMID 40051602, 2025). "In this study, the expression of Hsp90, GRP76, and UPR downstream effectors (ATF4, CHOP and sXBP1) were downregulated in in vivo and in vitro steatosis in response to AICAR administration." (PMID 36834782, 2023). "The PERK-eIF2α-ATF4 axis is one of the major arms for mammalian UPR response activation and has been found to be involved in lipogenesis and steatosis regulation." (PMID 36120597, 2022).
triple-negative breast carcinoma (18 papers, 2017 to 2025). An invasive breast carcinoma which is negative for expression of estrogen receptor (ER), progesterone receptor (PR), and human epidermal growth factor receptor 2 (HER2). "Upon GLS inhibition by CB-839 in triple-negative breast cancer, ATF4 accumulates, triggering the integrated stress response (ISR), upregulating genes related to amino acid biosynthesis and transport (e.g., PYCR1, ASNS, SLC7A5), and suppressing mTOR signaling." (PMID 40830338, 2025). "In triple-negative breast cancer, a high ATF4 expression was shown to be correlated with low OS after diagnosis (37 months for high ATF4 expression and 46 months for low ATF4 expression)." (PMID 36900220, 2023). "GLS1 inhibition in triple-negative breast cancer (TNBC) cell lines has been reported to lead to the accumulation of ATF4 protein." (PMID 35864117, 2022). "Here, we now identify the pathway in triple negative breast cancer cells that provides a sustained ATF4 response and enables their survival when encountering these challenges." (PMID 35963851, 2022). "ChaC glutathione-specific gamma-glutamyl cyclotransferase 1 (CHAC1) degradation of glutathione enhances cystine starvation-induced ferroptosis in triple-negative breast cancer cells via the GCN2-eIF2α-ATF4 pathway." (PMID 33672990, 2021). "Further, degradation of GSH caused by ATF4 target gene CHAC1 enhanced cystine starvation-induced ferroptosis by the GCN2-eIF2α-ATF4 axis in human triple-negative breast cancer cells." (PMID 33204324, 2020). "In contrast to the triple negative breast cancer cell lines, we also see a partial reduction in ATF4 expression using rapamycin and MK2206 in LN229 cells, suggesting the ability of additional signaling pathways to contribute to this stress response in these cells." (PMID 35963851, 2022). "In triple-negative breast cancer, a high ATF4 expression was shown to be correlated with low OS after diagnosis (37 months for high ATF4 expression and 46 months for low ATF4 expression); however, the difference between the two groups was not statistically significant (p = 0.125)." (PMID 34976799, 2021). "Distinctly, under conditions of metabolic and oxidative stress in triple negative breast cancers, we found that mTORC2 activation leads to elevated ATF4 expression, overall suggesting that ATF4 could serve as a biomarker for treatment with mTOR inhibitors in some cancers." (PMID 35963851, 2022). "qPCR analysis revealed that like the case in triple negative breast cancer, glutamine withdrawal resulted in increases in ATF4 and Sirt5 mRNA expression, and that Sirt5 mRNA transcript levels in cells deprived of glutamine were diminished upon the knockdown of ATF4." (PMID 35963851, 2022). "Recent data have shown how ATF4, MYC and mTORC1 stress-response pathways may converge in cancers that are reliant on glutamine, such as triple-negative breast cancer, where oncogenic MYC is a suspected driver of glutamine-reliance." (PMID 29940911, 2018).
Alzheimer disease (17 papers, 2014 to 2025). A progressive, neurodegenerative disease characterized by loss of function and death of nerve cells in several areas of the brain leading to loss of cognitive function such as memory and language. "DLK/JNK-mediated retrograde injury signaling is important in both in vitro and in vivo models of axonal insults, and retrograde signaling of axonally-translated ATF4 has been implicated in models of Alzheimer’s disease." (PMID 28440222, 2017). "By contrast, when we co-expressed the ATF4 reporter together with Aβ, a peptide that underlies Alzheimer′s disease, we observed dsRed induction, albeit at a reduced level." (PMID 25978358, 2015). "Consistent with our observation that both Ldh and ER-associated genes are altered in both Aß fly models and Alzheimer's disease patient brain, we have also shown that expression of Aß42 induces Ldh expression, and subsequent activity, in fly brain via ATF4, a downstream effector of the UPR." (PMID 33977265, 2021). "Recent studies have demonstrated that downregulation of ATF4 attenuates the endoplasmic reticulum stress-mediated neuroinflammation in mice model of Alzheimer's disease." (PMID 38913045, 2024). "Functionally, however, its role in early pathogenesis of Alzheimer's disease is far from clear, with studies in cells suggesting that the up-regulation of eIF2alpha phosphorylation and ATF4 activation contributes to cellular resistance to Aß toxicity." (PMID 33977265, 2021). "In particular, up-regulation of ATF4 has been observed in Alzheimer’s disease patients' brains, downstream of PERK activation and eIF2alpha phosphorylation." (PMID 33977265, 2021). "ATF4 is specifically synthesized locally in axons upon treatment with β-amyloid, the major component of the extracellular protein deposits found in Alzheimer’s disease (AD)." (PMID 32707908, 2020). "ATF4 expression is increased in the hippocampus of Alzheimer's disease (AD) murine models and the axons from AD cadavers, suggesting a potential role of ATF4 in the spreading of AD pathology." (PMID 28860159, 2017). "Intriguingly, activating transcription factor 4 (Atf4), whose excessive axonal translation spreads Alzheimer’s disease pathology across the brain, is also axonally translated at all stages tested." (PMID 27321671, 2016). "Alzheimer’s disease (AD) pathology includes transcriptional changes in the neurons, which are in part caused by the heterodimerization of two stress response transcription factors, CREB3L2 and ATF4." (PMID 40164587, 2025). "Thus, strong NGF induction mediated by Nrf2 and ATF4 in astrocytes may be promising for the prevention of Alzheimer’s disease, as the survival of cholinergic neurons that are specifically damaged in the early phase of Alzheimer’s disease is dependent on NGF." (PMID 30959808, 2019). "Using the model checking method, we verified several Alzheimer's disease and cancer-related properties, and also identified important proteins (NFκB, ATF4, ASK1 and TRAF2) in the ER-Golgi network, which might be responsible for the pathogenesis of cancer and AD." (PMID 25522186, 2014). "For instance, long exposure of axons to Aβ oligomers, involved in Alzheimer’s disease, drives the localization of the transcription factor Atf4, which is not triggered by acute Aβ treatment." (PMID 41212909, 2025). "In another work concerning ATF4, APP/PS1 mice (double transgenic mice expressing a chimeric mouse/human amyloid precursor protein and a mutant human presenilin 1 in their neurons), an established animal model of Alzheimer’s disease, was used." (PMID 29065505, 2017). "However, ATF4 is not the only protein for which translation is regulated by an eIF2-dependent mechanism that becomes disrupted in Alzheimer’s disease." (PMID 29065505, 2017).
Hyperglycemia (16 papers, 2010 to 2025). An increased concentration of glucose in the blood. "To further determine the role of ATF4/CHOP signaling in regulating KC activation by hyperglycemia, we utilized mannose-conjugated polymers to deliver CHOP siRNA (CHOP-siRNA) or its scramble control siRNA (SCR-siRNA) in vivo before IR in both CON and STZ mice." (PMID 29081777, 2017). "Recently it has been found that ATF4 mediates hyperglycemia-induced endothelial inflammation and retinal vascular leakage in mouse." (PMID 24993133, 2014). "The results showed that metformin significantly reduced the expression of ERS-associated proteins, such as PERK, ATF4, and CHOP, in hyperglycaemic osteoblasts; downregulating PPARγ levels enhanced the effect of metformin on PERK, CHOP and ATF4 in the context of hyperglycemia." (PMID 36951483, 2023). "ATF4 enhances the mRNA levels of amino acid metabolism- and redox-related genes while inducing the transcription of C/EBP homologous protein (CHOP) that causes ER stress-dependent apoptosis and hyperglycemia." (PMID 34547510, 2021). "However, absence of SESN2 did not completely inhibit the effect of Mg2+ on endothelial cells under hyperglycemia, suggesting other regulatory mechanisms such as ATF4 or SLC7A11 might make an impact." (PMID 38296940, 2024). "Melatonin administration has been shown to significantly relieve hyperglycemia-induced alterations in cellular growth, apoptosis, and calcium influx by inhibiting the cascade of the PERK–eIF2α–ATF4–CHOP signaling axis." (PMID 40496774, 2025). "Consistent with previous studies, hyperglycemia and long-term high-fat diets activated ER stress by upregulating GRP78, CHOP, and ATF4." (PMID 40276785, 2025). "Compared with Ctrl and NAC, in diabetic cardiac tissue under pathological condition of hyperglycemia, the activation of PERK signaling pathway was evidenced by increased phosphorylation of PERK, up- regulated expression of ATF-4 and CHOP in DCM group." (PMID 24180212, 2013). "Furthermore, lutein could reduce hyperglycemia-mediated ER stress in ARPE-19 cells by triggering the inositol-requiring enzyme 1(IRE1) -XBP1, activating transcription factor 4 (ATF4), and ATF6 pathways and their downstream activators." (PMID 39334773, 2024). "Interestingly, ATF4 and CHOP, but not ATF6 and s-XBP1, were further enhanced by hyperglycemia compared to the CON group." (PMID 29081777, 2017).